LINC00543 (long independently transcribed non-coding RNA 543)
Gene: Long non-coding RNA gene on chromosome 13 (27,953,526 to 27,955,370, forward strand). Ensembl gene ENSG00000260704.
Diseases named in the same sentence as LINC00543 in open-access papers:
LINC00543 is named in the same sentence as 2 diseases in open-access papers, as found by Europe PMC text mining. Sharing a sentence is not in itself a finding about the gene and the disease. The quoted sentences say what the papers report.
tumor (2 papers, 2023 to 2025). "Tumor formation and growth were inhibited upon the implantation of cell with the knockdown of LINC00543." (PMID 36841801, 2023). "Finally, our findings were further validated by demonstrating that LINC00543 regulated the tumour immune microenvironment in CRC by downregulating STAT1/STAT2 expression." (PMID 39868645, 2025). "Considering that EMT is a crucial process in tumor metastasis, we further interrogated whether LINC00543 promoted the EMT process." (PMID 36841801, 2023). "Besides, we found that the expression of LINC00543 was higher in the primary tumor tissues of CRC patients with distant metastasis than those without distant metastasis." (PMID 36841801, 2023). "Notably, the expression of LINC00543 in the invasive fronts was higher than in other regions of the primary tumor." (PMID 36841801, 2023).
LINC00543 also shares sentences with these, for which no sentence is quoted: colorectal cancer (1 paper).